PPIAP43 (peptidylprolyl isomerase A pseudogene 43)
Gene: Transcribed processed pseudogene on chromosome 11 (100,666,459 to 100,666,962, forward strand). Ensembl gene ENSG00000255059.
Diseases named in the same sentence as PPIAP43 in open-access papers:
PPIAP43 is named in the same sentence as 1 disease in open-access papers, as found by Europe PMC text mining. Sharing a sentence is not in itself a finding about the gene and the disease.
PPIAP43 shares sentences with these, for which no sentence is quoted: small cell lung carcinoma (1 paper).